CD38 (CD38 molecule)
Diseases named in the same sentence as CD38 in open-access papers (continued):
Sharing a sentence is not in itself a finding about the gene and the disease.
tumor (continued). "In addition, recent studies showed that daratumumab treatment results in the clustering of CD38 molecules into distinct polar aggregates, which can subsequently be released as tumor-derived microvesicles." (PMID 30294326, 2018). "The effect of loss of CD38 on metastasis is unlikely to result from its effect on primary tumor growth, since the primary tumors were excised when reached similar size both in WT and Cd38‒/‒ mice." (PMID 30159123, 2018). "Hence we generated inducible CD38-CAR T cells from (two) a low affinity CARs (CAR A4 and B1), which displayed much less off-tumor toxicity profiles than the high affinity CD38-CAR T cells." (PMID 29847570, 2018). "Here, we demonstrated that intratumoral CD38+ plasma cell density is an independent and incremental prognostic marker, even after adjusting for patient age, tumor grade, tumor size, lymph node status, and the density of tumor-infiltrating CD3+ T cells and CD20+ B cells." (PMID 29899747, 2018). "In line with this hypothesis, blocking CD38 enzyme activity in the tumor microenvironment may be a therapeutic strategy." (PMID 29636685, 2018). "Anti-CD38 immunotherapy is lethal to immunosuppressive CD38hi Breg/Treg cells and may improve anti-tumor T-cells function via modulating CLL immune-microenvironment." (PMID 30400835, 2018). "In the tumor microenvironment, CD38 may promote tumor growth by suppressing effector T cell responses." (PMID 30459772, 2018). "Importantly, CD38 inhibition on T-cells by anti-CD38 antibodies improved anti-tumor activity in mouse models by increasing NAD+ levels." (PMID 30294326, 2018). "In addition, when CD38 DNA aptamers loaded with Dox were administered systematically to MM tumor-bearing mice, a specific internalization of Dox into tumor cells, suppressed tumor growth, and increased survival was observed in the mice." (PMID 29617327, 2018). "Phagocytosis contributes to the anti-tumor activity of CD38-targeting antibodies." (PMID 30294326, 2018). "Daratumumab (Darzalex) is a monoclonal antibody that recognizes CD38 and induces tumor cell death not only through complement-dependent cytotoxicity (CDC) and antibody-dependent cell-mediated cytotoxicity (ADCC) but also through antibody-mediated cellular phagocytosis." (PMID 30445802, 2018). "The increased percentage of B cells in tumor may be a consequence of an increased number of CD27+CD38+/− B cells." (PMID 30774636, 2018). "Interestingly, compared with the TIM-1+B cells from the paired blood and peritumor liver samples, tumor-infiltrating TIM-1+B cells exhibited a CD5highCD24−CD27−/+CD38+/high phenotype, which is different from the conventional peripheral Breg phenotype." (PMID 30526680, 2018). "Thus, CD38 facilitates tumor growth by distinct microenvironment-dependent mechanisms in two different cancer microenvironments." (PMID 30159123, 2018). "This led us to hypothesize that eliminating them can potentially restore anti-tumor immune-effector response and is possible through anti-CD38 immunotherapy." (PMID 30400835, 2018). "Moreover, loss of CD38 from CD4+ T cells increased intrinsic NAD+ levels and led to metabolic reprograming of T cells with superior anti-tumor properties." (PMID 30159123, 2018). "CD38 antibodies kill tumor cells via Fc-dependent immune effector mechanisms including complement-dependent cytoxicity (CDC), antibody-dependent cell-mediated cytotoxicity (ADCC), antibody-dependent cellular phagocytosis (ADCP), and apoptosis upon secondary cross-linking." (PMID 30294326, 2018). "Anti-CD38 treatment may also generate resistance and induce tumor immune escape, through the up-regulation of two complement inhibitor proteins, CD55 and CD59 on MM cells." (PMID 30546360, 2018). "At the moment of development of resistance to a CD38 antibody-based treatment, an alternative treatment regimen can be selected based on several patient- and tumor-related factors, such as type of prior therapies, presence of comorbidities, and aggressiveness of relapse." (PMID 30294326, 2018).
tumor (continued). "CD38-targeting antibodies utilize multiple effector mechanisms including classic Fc-dependent immune effector mechanisms, but also the recently discovered immunomodulatory mode of action contributes to anti-tumor activity." (PMID 30294326, 2018). "Finally, fluorochrome-conjugated CD38 nanobodies efficiently reach CD38+ tumors in a rodent model within 2 h after intravenous injection, thus allowing in vivo tumor imaging." (PMID 30546360, 2018). "Anti-CD38 mAbs may also inhibit MM-activated CD38+ pDC precursors and/or restore DC maturation and presentation of tumor antigens, thereby further enhancing anti-tumor immunity." (PMID 28725493, 2017). "These nanobodies could potentially be used to monitor expression of CD38 on the cell surface of lymphocytes and tumor cells in daratumumab-treated patients." (PMID 29084989, 2017). "At 2 hours after injection, signals from the CD38+ tumor exceeded those of the kidneys." (PMID 29084989, 2017). "It will thus be interesting to determine whether allosteric modulation of CD38-enzyme activity in vivo by CD38 nanobodies can counteract its purported immunosuppressive and tumor promoting effects in the tumor microenvironment." (PMID 29084989, 2017). "However, ALK positive DLBCL constantly lack the expression of CD30 in immunohistochemistry, and strongly express plasma cell markers such as CD138 and CD38, which demonstrates the features of terminally differentiated B-lineage origin of the tumor cells." (PMID 27612448, 2016). "Thus, daratumumab is a CD38‐specific antibody that showed strong anti‐tumor activity in tumor models in vivo and engages multiple mechanisms of action." (PMID 26864107, 2016). "Furthermore, we showed that during treatment there was a significant decrease in CD38 expression on residual bone marrow‐localized MM cells as well as circulating tumor cells." (PMID 26864107, 2016). "We examined whether various Ca2+ signaling messengers produced by CD38 were actually involved in tumor cell-induced Ca2+ signals and degranulation in NK cells." (PMID 25879940, 2015). "Coupling of radionuclides may potentiate direct anti-tumor effects of monoclonal antibodies such as of CD38." (PMID 25576914, 2015). "IEC isolated from patients with non neoplastic disease provoked an increase in the proportion of activated CD8+CD38+ T-cell that was significantly blocked by the addition of anti-CD80 antibody, whereas no significant changes were observed in terms of CD4 activation." (PMID 25595911, 2015). "Accordingly, the anti-tumor effect of 213Bi-anti-CD38-MAb was different in each cell line." (PMID 25576914, 2015). "Moreover, the CD8+ T cells within the tumor showed a greater propensity towards activation as measured by increased co-expression of CD38/HLA-DR." (PMID 25436113, 2014). "Max-CD38 inhibited CD38+ tumor cell growth in both preventive and therapeutic settings." (PMID 22046572, 2011). "However, CD38+ NK cells produce low levels of IFN-γ and NAD+ and high levels of TGF-β and adenosine (ADO) and can promote Treg differentiation and macrophage polarization to tumor-associated macrophages (TAMs) to interrupt immune surveillance." (PMID 42292426, 2026). "Notably, CXCL16 (a ligand) from tumor cells and CXCR6 (a receptor) on HLA-DR+CD38+CD8+ T cells—previously implicated in enhancing anti-PD-1 therapy efficacy in other cancers—may mediate key tumor‒immune interactions." (PMID 41565617, 2026). "Therefore, we propose that small-molecule targeting of CD38 could mitigate the immunosuppressive milieu at the tumor site, fostering a favorable environment for Teffs and NK cells to mount an effective antitumor response." (PMID 40117361, 2025). "To validate this hypothesis, we subcutaneously implanted GL261 cells into WT and NFE2L1−/+ C57BL/6 mice and subsequently administered various treatments (Vehicle + IgG group, CD38 inhibitor group, Anti‐PD‐1 group, and CD38 inhibitor + Anti‐PD‐1 group) to evaluate their tumor‐inhibiting potential." (PMID 40677211, 2025).
tumor (continued). "Consequently, persistent CD38 upregulation could lead to T cell dysfunction by promoting a state of metabolic insufficiency and reduced anti-tumor or antiviral capacity." (PMID 41488275, 2025). "Additionally, the average fluorescence intensities (AFIs) of tumour tissue in the CD38‐EVsi.v and CD38‐EVsMNs groups were markedly higher compared to the EVsi.v and EVsMNs groups, respectively, with a significant statistical difference observed between the two MN groups." (PMID 40317915, 2025). "Second, the tumor’s genomic risk features (1q gain; extensive CNA burden) and driver spectrum overlapping MM raise concern for occult or future systemic disease, favoring a proteasome inhibitor–IMiD–anti-CD38 backbone with demonstrated activity in extramedullary settings." (PMID 41378284, 2025). "Additionally, CD38‐EVs‐Dox induced significantly greater cytotoxicity against the tumour cells than EVs‐Dox in vitro, and CD38‐EVs‐DoxMNs significantly reduced tumour burden compared to both EVs‐DoxMNs and CD38‐EVs‐Doxi.v, while maintaining favourable safety profiles." (PMID 40317915, 2025). "Although it remains unclear whether CD38 downregulation on tumor cells after mAb treatment is a marker of resistance or, instead, successful therapy, compelling preclinical and clinical data suggest that CD38 surface antigen density before treatment strongly correlates with mAb efficacy." (PMID 40453054, 2024). "Furthermore, CD8+CD38+ T cells were found to be independent prognostic factors for tumor response." (PMID 38404585, 2024). "Importantly, CD38 over expression in immune cells and tumor cells within the tumor microenvironment (TME) causes a reduction in NAD+ levels, leading to down regulation of the immune response against tumor cells." (PMID 36845935, 2023). "Also, apart from CD38, other NADases may also promote tumor cell immune escape, but to understand the specific role they play, further research is still needed." (PMID 38116009, 2023). "Therefore, treatment with CD38 antibodies may exhibit anti-tumor activity by releasing T-cell suppression via inhibition of such immunosuppressive cells, and may have therapeutic potential for solid tumors beyond hematologic malignancies such as MM." (PMID 36831262, 2023). "Therefore, it is also possible that high tumor burden and predisposition to BCG failure associated with increased frequency of intratumoral PD1+CD38+Tim3+ CD8+ T cells could be in part mediated by pro-tumorigenic immune subsets present at the tumor site." (PMID 37566017, 2023). "In addition, upon upregulation of CD38 expression, we observed an increase in the expression of PD-L1, and bioinformatic analyses also showed the aggregation of tumor infiltrating immune cells (TIICs), which indicated that the regulation by CD38 of the immune microenvironment requires further study." (PMID 36605482, 2023). "However, CD38‐CAR‐T cell therapy significantly inhibited tumor growth." (PMID 37039305, 2023). "Notably, CD38 expression decreased in the tumor fibrovascular stroma after IRX4647-treatment." (PMID 37689790, 2023). "Finally, STI-6643 displayed comparable anti-tumor activity to the high-affinity reference clone Hu5F9 in a RAJI-Fluc xenograft tumor model as monotherapy or in combination with anti-CD20 (rituximab) or anti-CD38 (daratumumab) mAbs." (PMID 35664753, 2022). "Targeting these CD38-expressing cells may help restore immune responses against tumor cells." (PMID 35943588, 2022). "However, CD38 on tumor cells displays more NAD+ hydrolase than ADPRC activity." (PMID 35342342, 2022). "However, agents targeting the adenosinergic pathway may hold promise, especially in tumours with high CD38 expression detected by IHC." (PMID 35054292, 2022). "Therefore, neoplastic clones expressing low CD38 levels could expand during treatment, and monocytes and granulocytes might favor the immune evasion of tumor cells." (PMID 36614086, 2022).
tumor (continued). "Determining whether CD38 regulates intracellular NAD+ level is functionally important because if confirmed, a cell-autonomous mechanism of CD38 loss, rather than a function mediated through the tumor microenvironment, may be inferred." (PMID 35677882, 2022). "High CD38 expression results in rapid depletion of NK cells after the daratumumab course (anti-CD38 monoclonal antibody), largely eliminating the source of innate immune cells, which could drive even more complete tumor eradication." (PMID 36077708, 2022). "Thus, we speculated that CD38-cADPR signal at least in partly through the activation of TRPM2 to promote the tumor survival." (PMID 34226519, 2021). "Metabolic reprogramming of NAD+ regulation via inhibition of CD38 has been proposed as a strategy for improving the efficacy of immune-based therapies and appears to play a significant role in the regulation of metabolism and immunomodulation of the tumor microenvironment." (PMID 33727923, 2021). "Moreover, CD38 could also play a significant role in the immunometabolism of the tumor microenvironment." (PMID 34760709, 2021). "Interestingly, this reduction in NK cells was not complete, and peripheral blood mononuclear cells (PBMCs) from the patients were still capable of inducing lysis by ADCC of CD38+ tumor cells in vitro, suggesting that persisting NK cells retained cytotoxic functionality." (PMID 32457357, 2021). "A rational strategy by affinity optimization has been established to diminish the undesired on-target off-tumor effects, and T cells expressing CD38-directed CARA4, which had reduced affinity (KD 10−7 M to 10−5 M), could selectively eliminate CD38++ MM cells, but spare CD38+ HPCs and T cells." (PMID 34627333, 2021). "Thus, we could speculate that CD38 in TILs may inhibit immune cell function to improve tumor proliferation." (PMID 34211854, 2021). "Baseline CD38 expression level on NKTCL tumor tissue also had no direct association with response, suggesting that a complex combination of NK-cytotoxic activity and tumor microenvironment modulation functions of daratumumab needs to be considered to dissect the contribution of antitumor effects." (PMID 33588922, 2021). "It is clear that the enzymatic and the surface receptor functions of CD38 are distinct from each other, and there is insufficient data available to justify which function of CD38 should be targeted for effective immune function restoration and hence, tumor elimination." (PMID 33727923, 2021). "It was surprising that increased CD38+ CD8+ T cells but not Tregs in the TME were associated with poor prognosis in NSCLC as Tregs may be the main suppressive cells to protect tumor cells from being attacked by the immune system." (PMID 33747957, 2021). "Thus, the intracellular distribution of CD38 may be an additional marker for assessing the biological effects of MCs in the tumor microenvironment." (PMID 34685490, 2021). "As alternative approaches, using the all-trans retinoic acid or the histone deacetylase inhibitor panobinostat could selectively upregulate the expression of CD38 on MM tumor cells that might augment CAR-T cell cytotoxicity, and diminish the toxicity on healthy cells." (PMID 33781320, 2021). "From the affinity measurement, RP02 bound to the purified CD38 with an apparent KD value of 8.6 × 10−9m and displayed a biphasic dissociation kinetics, much weaker than the KD value of the known scFv antibody 028 (0.65 × 10−9m), yet both showed similar efficacy in terms of tumor cell lysis." (PMID 33747727, 2021). "The combined activation of the inflammasome pathway, which leads to substantial MDSC recruitment, and CD38 activation, which reduces the sensitivity of tumor cells to IFN-γ through ADORA2a activation, may lead to a loss of therapeutic efficacy and uncontrolled tumor progression." (PMID 33467713, 2021). "However, the role of tumor expressed-CD38 on neoplastic formation and progression remains elusive." (PMID 34226519, 2021).
tumor (continued). "Therefore, we concluded that CD38 in TCs, FLCs, and TILs was actually engaged in tumor progression, indicating that CD38 could not only regulate the behavior of tumor cells but also affect the tumor microenvironment." (PMID 34211854, 2021). "Furthermore, cADPR could rescue the cell proliferation, colony formation, and migration in the CD38 KO and MU tumor cells." (PMID 34226519, 2021). "Finally, CD38 may enhance hypoxia signaling pathways in tumor cells or endothelial cells, leading to increased angiogenesis, immunosuppression and tumor proliferation." (PMID 33467713, 2021). "In contrast, cluster of differentiation 38 (CD38) has been demonstrated to act as a tumor suppressor gene in HNSCC, triggering pyroptotic cell death by activating NLRP3 and caspase-1; thus, by inhibiting CD38 expression, HNSCC cells might be able to escape NLRP3 inflammasome-mediated pyroptosis." (PMID 34064909, 2021). "In addition, we also found that CD38 had low expression in tumor tissue and N3 stage." (PMID 34760709, 2021). "Moreover, CD38-dependent signaling can impact on (tumor) angiogenesis." (PMID 33194619, 2020). "In addition, daratumumab, a mAb targeting CD38, has also shown promising efficacy in various clinical trials, and may achieve synergistic anti-tumor effects, together with PIs and IMiDs, in patients with RRMM." (PMID 32659909, 2020). "Indeed, CD38+ cells are present at higher density in the bone marrow and lymph node compartments, where interaction with activated T cells and vascular endothelium promotes tumor proliferation." (PMID 32225002, 2020). "It has been shown that shedding or transfer of daratumumab-CD38 complexes from tumor cells to extracellular fluids (“capping” followed by shedding) or to immune effector cells (“trogocytosis”) may result in reduced levels of CD38 on the tumor cell surface." (PMID 32041300, 2020). "In addition to catalyzing the production of Ado, CD38 may promote tumor development by inducing other tumor-supporting processes, e.g., angiogenesis in the TME, thus exerting functions beyond the CD38/CD203a/CD73 signaling." (PMID 33194619, 2020). "We suggest that these activities may reflect, in part, daratumumab mediated “trogocytosis” of CD38 (i.e., the transfer of the target molecule, CD38, together with bound antibody from the tumor cell to phagocytes mediated by FcγRs on the acceptor cells), and so the issue may be more complex." (PMID 33126570, 2020). "Daratumumab-induced on-tumor activity occurs through several CD38 immune-mediated actions (complement-dependent cytotoxicity, antibody-dependent cellular cytotoxicity, and antibody-dependent cellular phagocytosis), apoptosis, and modulation of CD38 enzymatic activity." (PMID 32001798, 2020). "Furthermore, they also demonstrated that CD38 knock out tumors exhibit delayed growth when compared to CD38+ wild-type tumors in wild-type mice and that in tumor-bearing mice, combination of anti-CD38 antibody and anti-PDL-1 acts synergistically to suppress tumor growth and dissemination." (PMID 32225002, 2020). "In addition, CCR5+, exhausted (PD-1+) T cell subsets were not detectable in the periphery, suggesting that T cell exhaustion of tumor surveilling populations and Treg activation through CD38 might be immune suppressive mechanisms exclusive to the iTME." (PMID 31462637, 2019). "Intra-tumoral upregulation of CD38 and subsequent adenosine production was recently identified as a mechanism of acquired resistance to PD-1/PD-L1 blockade and mAb-mediated or pharmacologic inhibition of CD38 was shown to significantly improve the anti-tumor efficacy of an anti-PDL-1 mAb." (PMID 31244820, 2019). "Thus, further work diving into the complexities of CD38 on both tumor cells and immune cells, as well as the expression and activity of other ectoenzymes with similar functions, need to be completed in order to provide a greater understanding of the role CD38 within solid tumors." (PMID 31878283, 2019).